CNST (consortin, connexin sorting protein)
Description:
Required for targeting of connexins to the plasma membrane.
Synonyms: C1orf71; FLJ32001; PPP1R64
Tractability: Antibody: UniProt places it where antibodies can reach, with high confidence; its Gene Ontology location is reachable by antibodies, with high confidence; UniProt predicts a signal peptide or a membrane-spanning region. PROTAC: ubiquitination databases record sites on it; its protein half-life has been measured.
Gene: Protein-coding gene on chromosome 1 (246,566,338 to 246,668,595, forward strand). Ensembl gene ENSG00000162852.
Subcellular location: Cell membrane; Golgi apparatus, trans-Golgi network membrane; Cytoplasmic vesicle, secretory vesicle
Subcellular location (Human Protein Atlas): Vesicles
Gene Ontology:
Molecular function: phosphatase binding; protein binding; connexin binding
Biological process: positive regulation of Golgi to plasma membrane protein transport
Cellular component: membrane; plasma membrane; protein-containing complex; trans-Golgi network; transport vesicle; Golgi apparatus
Genetic constraint (gnomAD): Loss-of-function variants: 29 observed, 50.34 expected, observed/expected ratio (o/e) 0.58, 90% interval 0.43 to 0.79. The upper end of that interval is the gene's LOEUF score, 0.79, which puts it in group 3 of 6, group 1 being the genes least tolerant of losing a copy. Missense variants: 761 observed, 787.17 expected, observed/expected ratio (o/e) 0.97, 90% interval 0.91 to 1.03. Synonymous variants: 289 observed, 296.53 expected, observed/expected ratio (o/e) 0.97, 90% interval 0.88 to 1.07.
Homologues: Orthologues: chimpanzee CNST (99% identical), macaque CNST (93% identical), pig CNST (80% identical), guinea pig CNST (77% identical), dog CNST (74% identical), mouse Cnst (68% identical), rat Cnst (68% identical), tropical clawed frog cnst (36% identical), zebrafish cnsta (24% identical), zebrafish cnstb (17% identical).
Diseases named in the same sentence as CNST in open-access papers:
CNST is named in the same sentence as 5 diseases in open-access papers, as found by Europe PMC text mining. Sharing a sentence is not in itself a finding about the gene and the disease. The quoted sentences say what the papers report.
acute myeloid leukemia (1 paper, 2022). Acute myeloid leukemia (AML) is a group of neoplasms arising from precursor cells committed to the myeloid cell-line differentiation. "During our search for possible new acute myeloid leukemia (AML) markers, we found that CNST was overexpressed in almost all patients with AML." (PMID 35662693, 2022).
leukemia (1 paper, 2022). A malignant (clonal) hematologic disorder, involving hematopoietic stem cells and characterized by the presence of primitive or atypical myeloid or lymphoid cells in the bone marrow and the blood. "We compared the expression levels of CNST in the leukemia cell lines Kasumi-1 and KO-52, where the Kasumi-1 cell line expresses RUNX1–RUNX1T1 and the KO-52 does not, and the results showed that the expression of CNST was higher in Kasumi-1 (Student’s t-test, p < 0.001)." (PMID 35662693, 2022).
lymph node metastasis (1 paper, 2021). "High circ-CNST expression might predict not only larger tumor size and shorter survival, but also lymph node metastasis in OS patients." (PMID 33962616, 2021). "Moreover, Chi-square test confirmed that circ-CNST level was significantly correlated with clinicopathologic features of OS patients, including TNM stage, lymph node metastasis, and tumor size." (PMID 33962616, 2021).
cancer (1 paper, 2022). A tumor composed of atypical neoplastic, often pleomorphic cells that invade other tissues. "Furthermore, we illustrated the expression of pyroptosis immune regulators across another∼10000 samples and revealed that CNST, GDF10, KCNC2, NAP1L2, NCOA7, and LINC00641 also revealed higher expression in cancer cells." (PMID 35620284, 2022).
CNST also shares sentences with these, for which no sentence is quoted: tumor (1 paper).